JAK2 (Janus kinase 2)
Diseases named in the same sentence as JAK2 in open-access papers (continued):
Sharing a sentence is not in itself a finding about the gene and the disease.
erythrocytosis (87 papers, 2006 to 2026). "Polycythemia vera (PV) is a chronic myeloproliferative neoplasm characterized by clonal erythrocytosis driven by JAK2 mutations, affecting more than 95% of patients." (PMID 42211159, 2026). "Older age, higher platelet count, higher hematocrit, higher absolute RBC count, and lower ferritin were also associated with JAK2-positive erythrocytosis (p < 0.01 for all comparisons)." (PMID 40806795, 2025). "A minority of patients with polycythemia (3/44, 6.8%) was preoperatively evaluated by a hematologist (including Janus kinase 2 [JAK2] mutational testing)." (PMID 40635339, 2025). "JAK2 mutations, particularly JAK2-Valine-to-Phenylalanine Substitution at Codon 617 (V617F), drive uncontrolled red blood cell production in polycythemia, increasing risks of complications." (PMID 40587754, 2025). "Older age (p < 0.01), higher platelet count (p < 0.01), and lower EPO (p < 0.01) were associated with JAK2 mutant erythrocytosis in a multivariate analysis." (PMID 40806795, 2025). "Looking specifically at components of the JAKPOT score, only the platelet count (p < 0.01) was associated with JAK2 mutant erythrocytosis after adjustment." (PMID 40806795, 2025). "We acknowledged the limitation of the retrospective design, as systematic exclusion of MPNs relied on EMR-documented diagnoses, and only 10 of 1145 erythrocytosis patients underwent JAK2 mutation testing, potentially missing MPN cases." (PMID 40640769, 2025). "Serum erythropoietin (EPO) level helps distinguish primary and secondary polycythemia, but it should be aided by further testing such as the JAK-2 gene mutation test." (PMID 39421127, 2024). "Genetic screening from peripheral blood shows a high sensitivity (95%-100%) for JAK2 (Janus kinase 2) mutations involving either exon 14 or 12, which helps distinguish PV from secondary polycythemia." (PMID 39371836, 2024). "In DP1, which was enriched with JAK2 mutation, most patients with PV characterized by erythrocytosis and/or panmyelosis were included." (PMID 39682306, 2024). "The most common cause of acquired primary erythrocytosis is the PV, a clonal myeloproliferative neoplasm caused by somatic, activating mutations occurring principally on the JAK2 tyrosine kinase." (PMID 38244120, 2024). "Erythrocytosis is caused by the expression JAK2, which is correlated with JAK/STAT pathway activation, promoting blood cell proliferation and inhibiting apoptosis." (PMID 39682300, 2024). "An audit was therefore performed to determine the clinical and laboratory impact of JAK2 V617F testing in patients with RCC-associated erythrocytosis." (PMID 37123102, 2023). "Despite molecular investigation having an inconsiderable impact on laboratory workload, this audit indicates that routine testing for latent JAK2 V617F-positive PV in patients with RCC-associated erythrocytosis is unnecessary." (PMID 37123102, 2023). "Despite the requirement for excluding secondary causes in the diagnostic workup of PV, RCC patients with an erythrocytosis are sporadically referred for molecular detection of the JAK2 V617F." (PMID 37123102, 2023). "As a consequence, the occurrence of an absolute polycythemia cannot be attributed to the sole demonstration of an isolated JAK2 E846D variant." (PMID 37239426, 2023). "As previously stated, the routine use of next generation sequencing (NGS) methods and whole exome/genome sequencing has shown light on other types of mutations in the JAK2 gene involved in the pathogenesis of erythrocytosis." (PMID 37239426, 2023). "In a routine practice, decreased values of serum erythropoietin EPO points to the primitive character of erythrocytosis, suggesting the role of driver JAK2 mutations in the occurrence of erythrocytosis." (PMID 37239426, 2023). "Altogether, our data as well as UK Biobank cohort analyses suggest that the occurrence of an absolute polycythemia cannot be attributed to the sole demonstration of an isolated JAK2 E846D variant." (PMID 37239426, 2023).
erythrocytosis (continued). "We analyzed the presence of EPOR variants in two patients with polycythemia in whom JAK2 pathogenic variants had been previously discarded." (PMID 36292571, 2022). "An audit was therefore performed to determine the clinical and laboratory impact of JAK2 V617F testing in patients with OSA-associated erythrocytosis." (PMID 36299528, 2022). "In this study we explored the mutation spectrum of patients with erythrocytosis using targeted myeloid NGS assay, and found that genetic variants in genes other than JAK2 are frequently observed in patients with erythrocytosis." (PMID 36290845, 2022). "Clinically, some studies have shown that patients with JAK2 exon 12 mutations are younger and present with erythrocytosis, but have similar symptoms and rates of survival when compared to patients with JAK2 V617F mutations." (PMID 34833034, 2021). "Generally, erythrocytosis-associated mutations in JAK2 are often associated with low EPO, whereas those in EPAS1 are often associated with increased EPO." (PMID 34946900, 2021). "The JAK2 p.V617F mutation was detected in 7 of the 501 patients tested, which accounts for 0.04% of the total cohort and 0.4% of patients with erythrocytosis." (PMID 33420222, 2021). "ET in children is very rare but has been reported and must be distinguished from hereditary erythrocytosis, which involves germline mutations in JAK2 or GSN (gelsolin gene)." (PMID 34833034, 2021). "in rare cases of erythrocytosis mutations in JAK2, exon 12 have been identified affecting residues between K537 and E543." (PMID 32823933, 2020). "A JAK2V617F-negative polycythemia associated with low serum epo needs to be tested for an exon 12 JAK2 mutation." (PMID 32477518, 2020). "Such influx of iron into the circulating compartment would be expected to result in recovery from iron deficiency, but JAK2 mutated patients, compared to patients with erythrocytosis and wild-type JAK2, instead exhibit greater iron deficiency." (PMID 30042411, 2018). "Patients with a JAK2 exon 12 mutation with a hematologic disorder consistent with the diagnosis of PV is characterized by erythrocytosis, with a raised hematocrit and hemoglobin level." (PMID 29167785, 2017). "Several somatic mutations of JAK2 exon 12 can be found in MPDs mainly characterized by erythrocytosis." (PMID 29167785, 2017). "More recently, additional mutations in the exon 12 of the JAK2 gene have been described in 5 to 10% of the patients with erythrocytosis." (PMID 20126644, 2010). "The JAK2 V617F mutant had constitutive kinase activity in vivo in the absence of Epo stimulation, and retroviral expression in murine BM caused erythrocytosis." (PMID 17183644, 2006). "Thus, we used our cohort of 650 patients with thoroughly explored erythrocytosis cases to explore the causality of the JAK2 E846D variant." (PMID 37239426, 2023). "Indeed, germline variants in the JAK2 gene have been reported to be a cause of familial erythrocytosis, such as the heterozygous germline JAK2 E846D substitution." (PMID 37239426, 2023). "Challenges of diagnosis between etiologies of erythrocytosis (PV versus SE) could be clarified after JAK2 somatic mutation genotyping is performed, as it prevails as a determinant tool in diagnosis." (PMID 35304527, 2022). "The discovery of JAK2 exons 14 and 12 mutations in 2005 and 2007, respectively, and their almost invariable association with PV has greatly simplified our current diagnostic approach to erythrocytosis." (PMID 34021251, 2021). "Rare JAK2 germline mutations have been associated with the hereditary type of erythrocytosis." (PMID 34440324, 2021). "The diagnostic workup of JAK2 unmutated erythrocytosis lacks uniformity, and often includes investigations for rare hereditary conditions and several acquired entities known to be associated with secondary erythrocytosis." (PMID 34021251, 2021).
erythrocytosis (continued). "These patients exhibit significantly higher hemoglobin levels and typically present with isolated erythrocytosis, suggesting that different regions of the JAK2 gene may be associated with different degrees of lineage restriction." (PMID 30042411, 2018). "However, in the family studied, co-segregation of the JAK2 E846D variant with erythrocytosis was limited to a nuclear family in which unaffected siblings could not be tested." (PMID 37239426, 2023). "A positive EPO-JAKPOT score had a Sn of 0.95 (95% CI, 0.83–0.98), Sp of 0.66 (95% CI, 0.58–0.72), −LR of 0.07 (95% CI, 0.02–0.30), and +LR of 2.7 (95% CI, 2.2–3.4) to diagnose JAK2 mutant erythrocytosis." (PMID 40806795, 2025). "A positive JAKPOT score had a Sn of 0.88 (95% CI, 0.73–0.94), Sp of 0.65 (95% CI, 0.57–0.72), −LR of 0.19 (95% CI, 0.08–0.44), and +LR 2.5 (95% CI, 2.0–3.2) for the diagnosis of JAK2 mutant erythrocytosis." (PMID 40806795, 2025). "Low EPO (<3.8 mU/mL) had a Sn of 0.77 (95% CI, 0.62–0.87), Sp of 0.98 (95% CI, 0.94–0.99), −LR of 0.23 (95% CI, 0.13–0.41), and +LR of 33 (95% CI, 12.5–89.6) for the diagnosis of JAK2 mutant erythrocytosis." (PMID 40806795, 2025). "In our cohort, the JAKPOT score was less sensitive for identifying patients with JAK2-positive erythrocytosis compared to the JAKPOT derivation study (Sn 0.88; 95% CI 0.74–0.95 vs. 0.95–1.0)." (PMID 40806795, 2025). "Patients with JAK2-positive erythrocytosis had a lower mean EPO than patients with JAK2-negative erythrocytosis (4.4 mU/mL vs. 12.3 mU/mL; p < 0.01)." (PMID 40806795, 2025). "We evaluated the diagnostic accuracy of EPO, JAKPOT, and a combination of low EPO and JAKPOT (EPO-JAKPOT) for predicting JAK2 mutant erythrocytosis." (PMID 40806795, 2025). "We expect that EPO-JAKPOT would have even better negative predictive value in primary care and other settings with a lower prevalence of JAK2 mutant erythrocytosis than what was observed in our study." (PMID 40806795, 2025). "JAK2 R1063H shows a weak induction of the JAK–STAT signal in hereditary erythrocytosis, and when JAK2 R1063H and JAK2 E846D coexist, they jointly induce a stronger JAK–STAT signal activation." (PMID 38618943, 2024). "In patients with confirmed JAK2 V617F mutation: ruxolitinib, a JAK1/2 kinase inhibitor, is used in the treatment of polycythemia." (PMID 39682300, 2024). "In a large French national cohort of 650 patients with well-characterized erythrocytosis, an isolated germline heterozygous JAK2 E846D substitution was observed in only two cases." (PMID 37239426, 2023). "Here, we show that blocking the CD47-SIRPα interaction results in the correction of polycythemia in a PV mouse model, which correlates with the expansion of splenic MerTK+ Mdcs and increased phagocytic activity of JAK2 mutant splenic macrophages against RBCs." (PMID 37095207, 2023). "Despite the role of STAT5 in JAK2-driven MPN promoting a PV phenotype, CALR mutation is unable to induce polycythemia or ligand independence when co-expressed with the EPO receptor." (PMID 32823933, 2020). "The JAK2 V617F-negative patients with erythrocytosis was diagnosed with PV according to 2008 WHO classification criteria and after thorough analysis of trephine biopsy." (PMID 30056580, 2018). "For example, administration of exogenous hepcidin has been shown to reverse erythrocytosis and splenomegaly in JAK2 V617F mice; the mechanism of action is likely sequestration of iron in splenic macrophages, inducing iron-restricted erythropoiesis." (PMID 30042411, 2018). "The mutation of the gene increases the phosphorylation activity of JAK2, promotes spontaneous cell growth, and induces erythrocytosis." (PMID 28877745, 2017).
erythrocytosis (continued). "JAK2 V617F mutation and methylation analysis of SOCS1/SOCS3 CpG islands were performed in 45 cases of MPNs, 42 cases of secondary erythrocytosis/thrombocythemia, and for 29 control individuals." (PMID 24385747, 2013). "In contrast to the polycythemia, the effect of JAK2 V617F on the leukocyte and platelet counts was more variable." (PMID 17183644, 2006). "Polycythemia and reticulocytosis responded to treatment with imatinib or a JAK2 inhibitor, but were unresponsive to the Src inhibitor dasatinib." (PMID 17183644, 2006). "In contrast to the polycythemia, the effects of JAK2 V617F expression on leukocyte and platelet counts were more variable." (PMID 17183644, 2006). "In the initial report, retroviral expression of JAK2 V617F in murine BM induced erythrocytosis in transplanted recipient mice, but the syndrome was not characterized further." (PMID 17183644, 2006). "In this report, we investigated the role of Src family kinases in the pathogenesis of JAK2 V617F-induced polycythemia." (PMID 17183644, 2006). "The polycythemia induced by JAK2 V617F was sustained for several months, but eventually hematocrit and reticulocyte counts returned to normal levels in both strains by 8 months after transplantation." (PMID 17183644, 2006). "Together, these results indicate that JAK2 V617F expression directly induces polycythemia in mice through Epo-independent overproduction of erythrocytes." (PMID 17183644, 2006). "The erythrocyte lifespan in JAK2 V617F recipients was normal, and polycythemia was accompanied by a proportional increase in red cell mass." (PMID 17183644, 2006). "Recent studies on JAK2-negative SGLT-2 inhibitor-associated erythrocytosis patients have reported a median hemoglobin increase of 2.3–2.5 g/dL." (PMID 40640769, 2025). "PV is also associated with the JAK2 V617F mutation; however, the patient does not have a history of erythrocytosis, making PV unlikely." (PMID 40104156, 2025). "We found that EPO-JAKPOT had high sensitivity (0.95; 95% CI 0.83–0.98) and a low −LR (0.07; 95% CI 0.02–0.30) for JAK2 mutant erythrocytosis, meaning that primary erythrocytosis could potentially be ruled out in an EPO-JAKPOT negative patient." (PMID 40806795, 2025). "An update on the diagnosis and management of JAK2 negative erythrocytosis describes that in the presence of a negative workup for erythrocytosis, the presence of HFE mutations should be considered." (PMID 39867034, 2024). "Little is known about Polycythemia cases where no JAK2 variants can be detected, and no other causes identified." (PMID 38244120, 2024). "If the serum erythropoietin level is low, PV should be considered and a quantitative JAK2 mutation assay should be obtained; if the serum erythropoietin level is high, secondary erythrocytosis should be considered and a JAK2 mutation assay is not necessary." (PMID 39598101, 2024). "Although some variants have been reported in JAK2-negative polycythemia, the causal genetic variants remain unidentified in ∼80% of cases." (PMID 37428608, 2023). "A similar analysis was performed with the use of NGS with a targeted panel for erythrocytosis performed on patients with idiopathic erythrocytosis (IE) negative for canonical JAK2 mutations and for secondary causes." (PMID 37239426, 2023). "In this study, we sought to evaluate the spectrum of genetic variants in patients with JAK2-negative polycythemia using whole exome sequencing." (PMID 37428608, 2023). "With very few previous studies targeting JAK2-negative polycythemia patients to identify underlying variants, this study opens a new avenue in evaluating and managing JAK2-negative polycythemia." (PMID 37428608, 2023). "It is imperative to evaluate patients lacking JAK2 mutations to identify additional genetic causes of erythrocytosis." (PMID 37428608, 2023).
erythrocytosis (continued). "We studied the clinical features of 121 patients with erythrocytosis of which 47 (38.8%) were JAK2 mutation‐positive and also fulfilled the diagnostic criteria for PV, and 67 (55.4%) JAK2 mutation‐negative erythrocytosis patients who were diagnosed as NNE." (PMID 35775283, 2023). "Through association analysis, we show that male patients presenting with idiopathic erythrocytosis, and normal EPO levels could be the best candidates for the search for the JAK2 GGCC_46/1 haplotype and CALR rs1049481_G allele." (PMID 36031623, 2022). "We also investigated Tier III variants, or variants of undetermined significance (VUSs), identified in JAK2-negative patients with erythrocytosis." (PMID 36290845, 2022). "Despite molecular investigation for the JAK2 V617F in OSA-associated erythrocytosis not affecting laboratory workload, this audit indicates that routine testing for PV is unnecessary." (PMID 36299528, 2022). "While OSA is a prevalent cause of secondary erythrocytosis the possibility exists of OSA-associated erythrocytosis and concomitant PV: a single case is identified in the literature with the PV unconfirmed by absence of JAK2 mutation analysis." (PMID 36299528, 2022). "The remaining 466 JAK2-negative patients were diagnosed with secondary erythrocytosis and mutations were found in 6% (28/466) of these cases." (PMID 36290845, 2022). "One year prior to his death, he was diagnosed with polycythemia (hemoglobin 20.6 g/dL) and tested for the JAK2 V617F variant with a negative result." (PMID 34501220, 2021). "For instance, LNK mutations were detected in 6 of 112 (5.3%) of patients with JAK2 negative erythrocytosis, assumed to be idiopathic." (PMID 34021251, 2021). "The increased utilization of peripheral blood JAK2 mutation screening has increased general awareness and recognition of non-PV erythrocytosis." (PMID 34021251, 2021). "Erythrocytosis is the defining feature in PV; however, owing to the driver lesion in the Janus-activated kinase 2 (JAK2) gene occurring at the hematopoietic stem cell level, multilineage involvement can result, leading to an overproduction of red cells, white cells, and platelets." (PMID 33817698, 2021). "In patients with polycythemia without a confirmed JAK2 mutation or underlying secondary cause, further investigations are challenging and not routinely conducted." (PMID 34946900, 2021). "Thus, it is recommended that patients with JAK2-V617F and exon 12-negative PV be tested with LNK gene sequencing to find any underlying germline causes for erythrocytosis." (PMID 34833034, 2021). "We present a long-term survey of pediatric liver recipients, evaluating prevalence, outcome and the main potential causes of erythrocytosis, including a comprehensive mutational analysis of commonly related genes (mutations of HBB and HBA, JAK2, EPOR, VHL, EPAS1 and EGLN1)." (PMID 32546701, 2020). "To further explore the regulation of iron metabolism in PV, we compared parameters of iron metabolism (unpublished data) in patients with erythrocytosis who lacked a mutation in JAK2 and those with a JAK2 mutation (i.e., V617F or exon 12)." (PMID 30042411, 2018). "The JAK2 V617F mutation was also identified in two patients with clinically suspected PV, who exhibited erythrocytosis but did not satisfy the clinical criteria for PV." (PMID 25624900, 2015). "The absence of JAK2 V617F and exon 12 mutations in addition to the lack of spontaneous erythroid colony formation pointed to a secondary cause of the erythrocytosis." (PMID 24312736, 2013). "Secondary erythrocytosis/ thrombocythemia patients and the control group were negative for the JAK2 V617F mutation, as expected." (PMID 24385747, 2013). "We previously reported several JAK2 V617F negative polycythemia patients with JAK2 exon 12 mutations detected by allele specific Polymerase Chain Reaction (AS-PCR)." (PMID 20126644, 2010).